ZCCHC13 (zinc finger CCHC-type containing 13)
Synonyms: 4930513O09RIK; Cnbp2; ZNF9L
Tractability: No criterion of Open Targets' tractability assessment is met for any kind of drug.
Gene: Protein-coding gene on chromosome X (74,304,180 to 74,305,034, forward strand). Ensembl gene ENSG00000187969.
Gene Ontology:
Molecular function: protein binding; mRNA binding; single-stranded RNA binding; translation regulator activity; nucleic acid binding; zinc ion binding
Biological process: positive regulation of cytoplasmic translation
Cellular component: cytoplasm
Homologues: Orthologues: macaque ZCCHC13 (81% identical), dog ZCCHC13 (68% identical), pig ZCCHC13 (66% identical), rat Zcchc13 (59% identical), mouse Zcchc13 (58% identical), tropical clawed frog cnbp (58% identical), zebrafish cnbpa (52% identical), zebrafish cnbpb (51% identical), Drosophila melanogaster CNBP (30% identical), Caenorhabditis elegans K08D12.3 (30% identical). Paralogues in human: CNBP (61% identical), ZCCHC7 (26% identical), ZCCHC9 (23% identical).
Diseases named in the same sentence as ZCCHC13 in open-access papers:
ZCCHC13 is named in the same sentence as 9 diseases in open-access papers, as found by Europe PMC text mining. Sharing a sentence is not in itself a finding about the gene and the disease. The quoted sentences say what the papers report.
hepatocellular carcinoma (1 paper, 2019). A malignant tumor that arises from hepatocytes. "In an effort to examine the clinical utility of ZCCHC13 in oncology, we investigated the expression of the ZCCHC13 mRNA and protein in hepatocellular carcinoma (HCC)." (PMID 30940166, 2019). "In the present study, we used hepatocellular carcinoma as a model to delineate the biological role of ZCCHC13 in cancers." (PMID 30940166, 2019). "Then, we tested the hypothesis that ZCCHC13 overexpression might be related to global DNA hypomethylation and promote hepatocellular carcinoma (HCC)." (PMID 30940166, 2019).
liver cancer (1 paper, 2019). An epithelial or non-epithelial malignant neoplasm that arises from the liver. "Based on these results, ZCCHC13 functions as an oncogene during the carcinogenesis of human liver cancer." (PMID 30940166, 2019). "In present study, we discovered that five CpG sites in the ZCCHC13 promoter region were significantly hypomethylated in human liver cancer cells and tissues." (PMID 30940166, 2019). "The intensity of densitometric imaging also showed remarkably higher levels of the ZCCHC13 protein in aggressive liver cancer cells compared with LO2 cells." (PMID 30940166, 2019). "In view of the emerging roles of ZCCHC13 in human liver cancers, we examined the expression of the ZCCHC13 protein in ten pairs of paraffin-embedded HCC specimens using immunohistochemistry." (PMID 30940166, 2019). "Liver cancer cells treated with the demethylating agent 5-Aza exhibited a dose-dependent increase in ZCCHC13 expression at both the mRNA and protein levels." (PMID 30940166, 2019). "Western blot analysis of multiple human cancer cell lines revealed that the normal liver cell line LO2 expressed the ZCCHC13 protein at much lower levels than common liver cancer cells." (PMID 30940166, 2019). "In this study, we observed ZCCHC13 overexpression in liver cancer cells." (PMID 30940166, 2019). "ZCCHC13 expression was frequently upregulated in human liver cancer cells and tissues." (PMID 30940166, 2019). "Here, we presented a comprehensive study of ZCCHC13 in human liver cancer." (PMID 30940166, 2019). "Moreover, overexpression of ZCCHC13 in liver cancer cells promoted cell cycle progression by facilitating the G1-S transition, which was related to aberrant activation of the ATK/ERK/c-MYC/CDK pathway." (PMID 30940166, 2019).
male infertility (1 paper, 2018). The inability of the male to effect fertilization of an ovum after a specified period of unprotected intercourse. "The molecular function and epigenetic regulation of ZCCHC13 expression in germ cells will enhance our understanding of current knowledge on abnormal methylation-derived male infertility." (PMID 29531833, 2018).
mental retardation (1 paper, 2019). "A large-scale systematic resequencing analysis revealed a potential correlation between the truncated variant of ZCCHC13 and X-linked mental retardation." (PMID 30940166, 2019).
prostate carcinoma (1 paper, 2019). A carcinoma that arises from epithelial cells of the prostate gland. "To analyze the relationship between ZCCHC13 expression and carcinogenesis, we detected the levels of the ZCCHC13 protein in a series of different human cancer cell lines, including lung, stomach, breast, cervical, and prostate cancer cell lines." (PMID 30940166, 2019).
cancer (1 paper, 2019). A tumor composed of atypical neoplastic, often pleomorphic cells that invade other tissues. "Western blot results revealed varying levels of the ZCCHC13 protein in cancer cells, ranging from clearly detectable to almost undetectable." (PMID 30940166, 2019). "The biological role of ZCCHC13 in cancers remains unknown, although it is expressed in the human testis." (PMID 30940166, 2019). "More importantly, the ZCCHC13 protein might be used as an immunogenic tumor antigen in cancer therapy." (PMID 30940166, 2019). "Of the genes identified in our previous study, we speculate that ZCCHC13 expression may be influenced by DNA methylation in human cancers." (PMID 30940166, 2019). "However, the function of ZCCHC13 in cancer has yet to be determined." (PMID 30940166, 2019). "Previous studies have shown that zinc-finger CCHC-type containing 13 (ZCCHC13) is located in an imprinted gene cluster in the X-inactivation centre, but few published studies have provided evidence of its expression in cancers." (PMID 30940166, 2019).
tumor (1 paper, 2019). "In summary, our study revealed that ZCCHC13 is expressed at high levels in HCC tumor tissues and is closely associated with DNA hypomethylation of the promoter region." (PMID 30940166, 2019). "The average beta values for the ZCCHC13 promoter in tumor samples (n = 204) were much lower than in matched normal samples (n = 65) (p < 0.005)." (PMID 30940166, 2019). "Similar to the trends observed in cell lines, the ZCCHC13 promoter was significantly hypomethylated in tumor tissues compared with normal tissues." (PMID 30940166, 2019). "The AKT/ERK/c-MYC signaling pathway played an important role in the ZCCHC13-evoked increase in tumor cell growth." (PMID 30940166, 2019). "Positive signals for ZCCHC13 staining were detected in all tumor tissues." (PMID 30940166, 2019). "Immunoblots revealed that ZCCHC13 expression was frequently upregulated in 78.6% (48/61) of tumor tissues compared with 5% (3/60) of nontumor tissues." (PMID 30940166, 2019). "The quantitative analysis revealed significantly higher levels of the ZCCHC13 protein in tumor tissues than in adjacent nontumor tissues." (PMID 30940166, 2019). "The levels of the ZCCHC13 protein were increased in HCC tumor tissues compared to nontumor tissues." (PMID 30940166, 2019). "Furthermore, 10 tumor tissues and 10 matched nontumor tissues were collected to validate the ZCCHC13 promoter methylation status in HCC tissue sections." (PMID 30940166, 2019).
ZCCHC13 also shares sentences with these, for which no sentence is quoted: Azoospermia (2 papers); glioma (1).